FGFR4 (fibroblast growth factor receptor 4)
Diseases named in the same sentence as FGFR4 in open-access papers (continued):
Sharing a sentence is not in itself a finding about the gene and the disease.
breast cancer (continued). "Our data highlighting effective targeting of oncogenic FGFR2 and FGFR4 alterations in specific PDX led us to analyze the METABRIC and TCGA datasets using cBioPortal to determine the frequency of FGFR2 and FGFR4 genomic and expression changes in different breast cancer subtypes." (PMID 34344433, 2021). "Currently, the mechanisms underpinning FGFR4 overexpression in breast cancer are unclear." (PMID 34344433, 2021). "The occurrence of FGFR4 genomic and/or expression changes in particular breast cancer subtypes and the association of these changes with poor prognosis led us to further interrogate FGFR4 function using a panel of breast cancer PDOs spanning the luminal A, HER2 and TNBC subtypes." (PMID 34344433, 2021). "Importantly, our studies support a role for FGFR4 as a therapeutic target in specific breast cancer subtypes." (PMID 34344433, 2021). "In addition, we discovered six genes: CCNE1, CEP55, EGFR, EXO1, FGFR4, and MAPT associated with both types of breast cancer." (PMID 32724790, 2020). "Significantly increased FGFR4 expression was observed in doxorubicin-resistant breast cancer cells, and knockdown of FGFR4 could increase sensitivity to doxorubicin." (PMID 32154250, 2020). "In breast cancer, upregulation of FGFR4 is partly due to gene amplification." (PMID 32154250, 2020). "These tumor-targeting approaches could be further applied to other FGFR4-expressing tumors, such as hepatocellular carcinomas, head and neck squamous cell carcinomas, and basal-like breast cancer." (PMID 33182650, 2020). "Previous research has shown that high levels of FGFR4 mRNA could be an independent predictive factor, as high levels of FGFR4 show shorter progression-free survival in breast cancer patients treated with tamoxifen." (PMID 32710281, 2020). "Consistently, MDA-MB-453 (ER−, PR−, HER2+) as well as ZR-75.1 and BT474 (ER+, PR+/−, HER2+) breast cancer cells expressed FGFR4, whereas both FGFR4 and HER2 were low in MCF7 and T47D (ER+, PR+/−, HER2−), and negligible in triple-negative (ER−, PR−, HER2−) cells." (PMID 30903103, 2019). "In another study, elevated FGFR4 mRNA levels were detected in 32% of breast cancer samples." (PMID 30634399, 2019). "Interestingly, the amplified FGFR4 gene was identified in 10% of breast cancer, which more frequently harbors estrogen- and progesterone-receptor with lymph-node metastases." (PMID 30634399, 2019). "As FGFR4 is suitable for targeting, these results raise tempting questions, whether FGFR4 inhibition in HER2+ breast cancer would release the intrinsic MST1/2-mediated apoptotic machinery." (PMID 30903103, 2019). "Moreover, pharmacological FGFR4 inhibition specifically sensitized the HER2+ MDA-MB-453 breast cancer cells, not only to HER2/EGFR and AKT/mTOR inhibitors, but also to clinically relevant apoptosis modulators." (PMID 30903103, 2019). "Since FGFR4 upregulation and activation has been recently shown to confer chemoresistance in breast cancer cells, we asked whether inhibition of the FGFR4/FGF19 axis might enhance chemotherapy sensitivity in cancer cells." (PMID 27192118, 2016). "Next, we sought to investigate the mechanism by which FGFR4 might be constitutively activated in a subset of breast cancer cells." (PMID 27192118, 2016). "To evaluate whether the pro-survival effects of FGFR4 in breast cancers cells could be mediated through aberrant activation of these pathways, we analyzed the effects of FGFR4 knockdown on these targets using a panel of phospho-specific antibodies." (PMID 27192118, 2016). "Moreover, FGFR4 amplification or overexpression, which are associated with a poor clinical prognosis, are observed in hepatocellular carcinoma (HCC), breast cancer, colon cancer, pancreatic cancer, prostate cancer, and neuroastrocytoma." (PMID 27618313, 2016). "Of note, the FGFR4 protein was found to be phosphorylated in breast cancer cells that express it, suggesting that FGFR4 might be constitutively active in these cancer cells." (PMID 27192118, 2016).
breast cancer (continued). "To determine whether depletion of endogenous FGFR4 has any effect on the proliferation and survival of breast cancer cells that exhibit constitutively active FGFR4, we performed lentiviral shRNAs-mediated knockdown of FGFR4 in a panel of breast cell lines." (PMID 27192118, 2016). "Additionally, the Y367C mutation, which is outside of the FGFR4 kinase domain, causes FGFR4 to form a homo-dimer spontaneously, resulting in the constitutive activation of the FGFR4 signaling pathway in MDA-MB453 breast cancer cells." (PMID 27618313, 2016). "FGFR4 encodes a member of the fibroblast growth factor receptor family, and implicated in the tumorigenesis of many types of cancers, such as HCC, prostate cancer, breast cancer, pancreatic cancer." (PMID 26296091, 2015). "In this study, we genotyped two polymorphisms in the FGFR4 gene, rs1966265 and rs351855, and two polymorphisms in the FGFR3 gene, rs2234909 and rs3135848, and evaluated their association with breast cancer risk in women from Heilongjiang Province, northeast of China." (PMID 26431494, 2015). "We can speculate that FGFR2 functions as a tumor suppressor in breast cancer, as well as FGFR4, for which functions are still unknown." (PMID 21108794, 2010). "It was demonstrated that FGFR4 Arg388 was not involved in tumour initiation, as the FGFR4 alleles showed a similar distribution in breast cancer patients and healthy controls and appeared in approximately 50% of the human population." (PMID 16721364, 2006). "The presence of soluble transcripts of FGFR4 have also recently been described and implicated in the modulation of FGF in MCF7 breast cancer cells, suggesting that soluble FGFRs may be a feature of tumour cells where they disrupt the FGF/FGFR function." (PMID 14520460, 2003). "HLF and FGFR4 may be potential drug development targets for preventing and treating breast cancer." (PMID 39664391, 2024). "Therefore, we speculated that FGFR4 inhibition overcomes anti-HER2 resistance by triggering ferroptosis in breast cancer." (PMID 35562334, 2022). "Therefore, inhibition of FGFR4 might be a strategy for increasing sensitivity to multiple anti-HER2 strategies in breast cancer." (PMID 35562334, 2022). "Therefore, we chose FGFR4 for further investigation to validate whether it could be a target to overcome anti-HER2 resistance in breast cancer." (PMID 35562334, 2022). "Finally, increasing evidence supports subtype-selective roles for FGFR4 in breast cancer." (PMID 34344433, 2021). "In addition, FGFR4 is overexpressed in metastases derived from luminal A breast cancers compared to the primary tumor and high FGFR4 expression and hotspot mutations occur in endocrine therapy-treated distant breast cancer metastases, particularly derived from invasive lobular carcinoma." (PMID 34344433, 2021). "Moreover, a recent study has determined that FGFR4 drives phenotypic switching of luminal A breast cancers to a HER2-enriched gene expression phenotype, and that a FGFR4-induced expression signature is positively associated with poor outcome and site-selective metastasis." (PMID 34344433, 2021). "Moreover, FGFR4 is not only implicated in RMS tumorigenesis, but drives tumor progression in FGF19 expressing hepatocellular carcinomas, head and neck squamous cell carcinomas, and basal-like breast cancer." (PMID 33182650, 2020). "Furthermore, FGFR4 (FGFR4 G388A) was identified in ES and breast cancer patients, but its functional role remains unclear." (PMID 32754598, 2020). "Importantly, the specific knockdown or short-term inhibition of FGFR4 in endogenous models of human HER2+ breast cancer cells likewise led to increased MST1/2 activation, in conjunction with enhanced MST1 nuclear localization and generation of N-terminal cleaved and autophosphorylated MST1." (PMID 30903103, 2019). "However, the rs351855 G>A polymorphism did not alter the tyrosine kinase activity of FGFR4 in breast cancer and prostate cancer cells." (PMID 28445975, 2017).
breast cancer (continued). "Importantly, the co-expression of FGFR4/FGF19 is significantly associated with AKT phosphorylation, Ki-67 staining, higher tumor stage and basal-like phenotype (triple-negative and CK5/6 positivity) in breast cancers." (PMID 27192118, 2016). "Overexpression of FGFR4 was observed in several cancers and has been reported to be associated with aggressive tumors and poor prognosis in breast cancer, squamous cell carcinoma, ovarian cancer, non-small cell lung cancer, gastric cancer, as well as colorectal cancer." (PMID 27650548, 2016). "G388R mutation of the FGFR4 gene is not relevant for breast cancer prognosis." (PMID 14710228, 2004). "Considering the preclinical data presented in breast cancer, investigating the vulnerability of primary HER2E tumors specifically to FGFR4 inhibition appears relevant." (PMID 40044693, 2025). "These included several well-known cancer genes or their family members with previously less recognized role in breast cancer—FGFR3, FGFR4, NOTCH3, KMT2B, EP300, FLT4 and FAT1." (PMID 40858906, 2025). "Recent studies have shown that FGFR4 inhibition can reverse therapy resistance, particularly in HER2-positive breast cancer, suggesting that FGFR4 is not only a prognostic marker but also a potential therapeutic target." (PMID 40806692, 2025). "In this study we demonstrate that the regulator of FGFR4 mRNA expression are not somatic variants or copy number alterations but instead appears to be DNA hypomethylation of regions in the gene’s promoter, acting as an apparent switch for FGFR4 expression in breast cancer." (PMID 40044693, 2025). "Patient-derived xenografts and organoid models revealed that roblitinib, a selective FGFR4 inhibitor (also known as FGF-401), is effective in both intrinsic and acquired anti-HER2-resistant breast cancers." (PMID 39664391, 2024). "The synergistic effect of anti-FGFR4 and anti-HER2 therapies in breast cancer with intrinsic or acquired resistance." (PMID 38344206, 2024). "And FGFR4 promoted cell proliferation and suppressed cell apoptosis via activating MST1/2 in breast cancer." (PMID 39658878, 2024). "All these findings highlight the significance of FGF19/FGFR4 in treatment resistance phenomenon in breast cancer; thus, more thorough studies are necessary to explore the clinical significance of the FGF19/FGFR4 axis to improve patient outcomes." (PMID 39796710, 2024). "To investigate the expression pattern of FGFR4 in breast cancer, we downloaded the TCGA‐BRCA cohort and found that FGFR4 expressed higher in breast cancer samples than in normal tissues." (PMID 39658878, 2024). "Similar to FGFR4/ERBB2, the overall correlation between GPR160 and TMEM45B expression in TCGA breast cancers appeared in the lower spectrum (Spearman rho = 0.35)." (PMID 37857634, 2023). "Roblitinib, a highly selective inhibitor of FGFR4, combats anti-HER2 resistance by inducing ferroptosis in refractory HER2-positive breast cancer." (PMID 38072908, 2023). "A strong positive correlation between FGFR4 expression and SLC7A11 or FPN1 expression was discovered in HER2-positive breast cancer." (PMID 35562334, 2022). "In our study, FGFR4 phosphorylated GSK-3β to activate β-catenin/TCF-4 signaling and drive anti-HER2 resistance in breast cancer." (PMID 35562334, 2022). "Certainly, FGFR4 cooperates with HER2 to regulate the expression of cyclin D and promote breast cancer cell proliferation." (PMID 35193394, 2022). "As the canonical FGF8 receptors FGFR2c and FGFR3c are expressed at low level in breast cancer cells, it is possible that FGF8 acts in an autocrine manner on FGFR1 and FGFR4, which are instead present in the breast epithelium." (PMID 35193394, 2022). "Time-lapse movie recorded the morphological changes before cell death after FGFR4 inhibition in rSKBR3 and MDA-MB-453 resistant breast cancer cells." (PMID 35562334, 2022).
breast cancer (continued). "The FGF19/FGFR4 axis has been connected to dismal patient prognosis and disease progression in different tumor entities including HCC and breast cancer." (PMID 35484633, 2022). "Here, we discover that FGFR4 expression is upregulated, which confers anti-HER2 resistance by attenuating ferroptosis in breast cancer." (PMID 35562334, 2022). "Together, our data demonstrated that m6A RNA hypomethylation resulted in FGFR4 upregulation, which confers anti-HER2 resistance to breast cancer." (PMID 35562334, 2022). "Patient-derived xenograft and organoid models reveal the potent efficacy of roblitinib (a selective inhibitor of FGFR4; also named as FGF-401) in both intrinsic and acquired anti-HER2 resistant breast cancer." (PMID 35562334, 2022). "The FGFR4 Y367C activating mutant was discovered in MDA-MB-453 cells, a HER2-positive breast cancer cell line that is extremely sensitive to roblitinib." (PMID 35562334, 2022). "Among breast cancer subtypes, TNBC/basal breast cancer patients with high FGFR4 expression and luminal A patients with amplified FGFR4 displayed a significantly worse overall survival." (PMID 34344433, 2021). "In the TCGA dataset, 126 out of 994 (13%) breast cancer patients have FGFR2 (7%) and/or FGFR4 (6%) alterations." (PMID 34344433, 2021). "The signaling of FGF receptor-19 (FGFR19) and FGFR4 enabled the survival of breast cancer cells lines co-expressing them via the activation of PI3K/Akt pathway, targeting FGFR4/FGF19-sensitized cancer cells to death." (PMID 33854965, 2021). "In the METABRIC dataset, 247 out of 1904 (13%) breast cancer patients have FGFR2 (6%) and/or FGFR4 (7%) alterations." (PMID 34344433, 2021). "Accordingly to Next Generation Sequencing (NGS) investigating FGFR levels in breast cancer, low levels of FGFR3 and FGFR4 were detected." (PMID 32188012, 2020). "It was shown that besides p38, MKK3 can bind to multiple other proteins, including several drivers of breast cancer, such as CDK4, AURKA, FGFR4, EPHA2, and MYC." (PMID 32873298, 2020). "Our results suggest that the PR status has a profound effect on tyrosine kinases, especially for FGFR4 and LCK genes, in ER+/HER2− breast cancer patients." (PMID 32710281, 2020). "Overexpression of FGFR4 has been reported in several solid tumors including hepatocellular carcinoma (HCC), breast cancer, oropharyngeal squamous cell carcinoma (OPSCC), and pancreatic cancer." (PMID 32154250, 2020). "An integrated molecular analysis of breast carcinoma has evidenced that HER2+ breast tumors harbor high expression levels of many receptor tyrosine kinases, including FGFR4." (PMID 33081025, 2020). "Recently, FGFR4 has been shown to activate AKT16 and inhibit MST1/217 signaling in breast cancer cells, but the role of FGFR4 in ILC remains uncertain." (PMID 31263748, 2019). "Blockade of this phosphorylation by Y433F mutation induced MST1 activation, as indicated by increased threonine phosphorylation of MST1/2, and the downstream substrate MOB1, in FGFR4-overexpressing T47D and MDA-MB-231 breast cancer cells." (PMID 30903103, 2019). "The FGFR4 rs1966265 and FGFR2 rs2981578 contributed to clinical outcome of breast cancer treated with docetaxel–epirubicin-cyclophosphamide (CET)-based chemotherapy." (PMID 30359238, 2018). "Furthermore, the combination of anti-fibroblast growth factor receptor 4 (FGFR4) and anti-HER2 therapies has been identified as a mechanism to trigger ferroptosis in HER2-positive breast cancer." (PMID 40427552, 2025). "Additionally, research has found that the inhibition of FGFR4 affects the expression of β-catenin/TCF4-SLC7A11 and FPN1, which has a significant impact on ferroptosis in HER2-positive breast cancer cells, thereby enhancing treatment sensitivity." (PMID 40009842, 2025). "Additionally, m6A methylation modification of FGFR4 can inhibit ferroptosis, enhancing the resistance of HER2-positive breast cancer cells to anti-HER2 therapy." (PMID 40009842, 2025).
breast cancer (continued). "The down-regulation of METTL14 leads to reduced fibroblast growth factor receptor 4 (FGFR4) mRNA decay through m6A RNA hypomethylation, thus initiating the β-catenin/TCF4-SLC7A11/FPN1 pathway to develop anti-HER2 resistance in breast cancer by attenuating ferroptosis." (PMID 38988324, 2024). "Moreover, m6A hypermethylation resulting from METTL14 modification and YTHDC2 modulation led to the upregulation of FGFR4, which inhibited ferroptosis and conferred anti-HER2 resistance to breast cancer." (PMID 38550378, 2024). "Furthermore, Zou and the team found that trastuzumab targets the resistance-related gene FGFR4, inhibiting ferroptosis through the FGFR4-βcatenin/TCF4-SLC7A11 axis and promoting resistance in HER2-positive breast cancer." (PMID 39664391, 2024). "FGFR4 was specifically selected as a gene overexpressed in HER2ENC7, but it displays a lesser correlation to ERBB2, a prototypical HER2ENC gene, in SCAN-B data but also TCGA breast cancers when analyzed through the cBioPortal online tool (Spearman rho = 0.24)." (PMID 37857634, 2023). "To examine whether FGFR4 expression correlates with intrinsic anti-HER2 resistance, we performed IHC staining using 36 HER2-positive breast cancer biopsies obtained before administration of anti-HER2 based neoadjuvant therapy." (PMID 35562334, 2022). "Consequently, these findings further support a role of FGFR4 in GBM recurrence in a highly aggressive GBM subset based on an autocrine loop connecting FGF19 and FGFR4, as previously reported in breast cancer." (PMID 35484633, 2022). "In contrast, FGFR2 and FGFR3 were not significantly correlated with any subgroup of breast cancer cell lines, whereas FGFR4 expression was elevated in HER2 and luminal cell lines." (PMID 33772015, 2021). "Co-expression of FGFR4 and FGF19 was observed in about 30% of primary breast cancers." (PMID 32154250, 2020). "Moreover, in breast cancer, autocrine FGF19/FGFR4 signaling is important for cell survival, and FGF19/FGFR4 co-expression was observed in primary breast tumors." (PMID 33066597, 2020). "Nevertheless, current results show that active FGFR4 tyrosine phosphorylates and inactivates the pro-apoptotic MST1/2 serine/threonine kinase in breast cancer cells, thus revealing a novel mechanism of RTK-mediated apoptosis evasion and oncogenic FGFR4 function." (PMID 30903103, 2019). "In breast cancer cells, it was recently shown that FGFR4 is highly overexpressed at mRNA level in a panel of 6 breast cancer cells from different cancer subtypes in comparison to non-transformed breast myoepithelial control cells, including MCF7 and SKBR3." (PMID 28376106, 2017). "We found that FGFR4 is overexpressed in a subset of breast cancer cell lines but not in the normal myoepithelial cells." (PMID 27192118, 2016). "Together, our results implicate that FGFR4 and FGF19 autocrine signaling may serve as a potential therapeutic target for the treatment of refractory basal-like breast cancers." (PMID 27192118, 2016). "Importantly, a subset of basal-like breast cancer cells also secrete fibroblast growth factor 19 (FGF19), a canonical ligand specific for FGFR4." (PMID 27192118, 2016). "FGFR3 and FGFR4 amplification are less common than FGFR1 and FGFR2 in breast cancer." (PMID 27489863, 2016). "In addition, FGFR4 may be constitutively-activated or overexpressed in a variety of human neoplasias, including hepatocellular carcinoma, prostate cancer, rhabdomyosarcoma and breast cancer, and the potential utility of FGF19 and/or FGFR4 as a target for growth inhibition has been proposed." (PMID 21203561, 2010). "Further inhibition of FGFR4 in drug-resistant cells revealed that the expression of SLC7A11 and GPX4 was significantly reduced, which promoted ferroptosis to inhibit tumorigenesis, thus restoring the sensitivity of drug-resistant breast cancer cells to anti-HER2." (PMID 38550378, 2024). "SNPs in FGFR4 but not in FGFR3 were strongly correlated with breast cancer." (PMID 34830836, 2021).